ANXA2P3 (annexin A2 pseudogene 3)
Synonyms: LIP2; formerly ANX2P3; ANX2L3; LPC2C
Gene: Processed pseudogene on chromosome 10 (64,825,572 to 64,826,579, forward strand). Ensembl gene ENSG00000216740.
Diseases named in the same sentence as ANXA2P3 in open-access papers:
ANXA2P3 is named in the same sentence as 7 diseases in open-access papers, as found by Europe PMC text mining. Sharing a sentence is not in itself a finding about the gene and the disease. The quoted sentences say what the papers report.
glioma (3 papers, 2017 to 2022). A benign or malignant brain and spinal cord tumor that arises from glial cells (astrocytes, oligodendrocytes, ependymal cells). "The annexin A2 pseudogenes (ANXA2P1, ANXA2P2, and ANXA2P3) are significantly upregulated in glioma and are associated with adverse outcome of glioma patients." (PMID 31681595, 2019). "Based on a pseudogene-mining approach, high risk scores of six-pseudogene signature (including ANXA2P3) predicted poor OS of glioma patients." (PMID 29291003, 2017). "Six pseudogenes (SP3P, ANXA2P3, PTTG3P, LPAL2, CLCA3P, and TDH) were reported to be associated with overall survival in glioma." (PMID 36333286, 2022). "A prior report that constructed another signature with six pseudogenes (SP3P, ANXA2P3, PTTG3P, LPAL2, CLCA3P, and TDH) for prediction of glioma patient survival." (PMID 31681595, 2019).
biliary atresia (1 paper, 2020). A rare, biliary tract disease characterized by progressive obliterative cholangiopathy of the intra- and extrahepatic bile ducts, occurring in the embryonic/ perinatal period, leading to severe and persistent neonatal jaundice and acholic stool. "Expression levels of ANXA2 as well as ANXA2P3 are also upregulated in liver tissues of biliary atresia patients, indicating that ANXA2P3 may be involved in the pathophysiology of biliary atresia development." (PMID 32154257, 2020).
glioblastoma (1 paper, 2017). The most malignant astrocytic tumor (WHO grade IV). "In this study, Differentially Expressed Pseudogenes (DEPs) between glioblastomas and non-tumor controls were found by bioinformatics analysis, of which the annexin A2 pseudogenes (ANXA2P1, ANXA2P2 and ANXA2P3) were significantly up-regulated, along with the parent gene annexin A2 (ANXA2)." (PMID 29291003, 2017).
ovarian carcinoma (1 paper, 2017). A malignant neoplasm originating from the surface ovarian epithelium. "Through integrated analysis of several ovarian cancer datasets, a 19-gene model which including ANAX2P1 and ANXA2P3 can serve as a reproducible predictor of survival." (PMID 29291003, 2017).
cancer (2 papers, 2007 to 2017). A tumor composed of atypical neoplastic, often pleomorphic cells that invade other tissues. "Seven (PA2G4P4, ATP5EP2, FTH1P3, ANXA2P3, ANXA2P1, HNRNPA1P33, and HSP90B3P) of the 14 pseudogenes that our analysis revealed as important for pan-cancer classification were previously found to be differentially expressed in various cancers." (PMID 28673244, 2017). "Although ANXA2 (annexin A2) is a substrate for a variety of protein kinases, and plays an important role in plasmin regulation and in cancer cell invasiveness and metastasis, ANXA2P3 (annexin A2 pseudogene 3) is a novel marker not being previously reported." (PMID 17411443, 2007).
ANXA2P3 also shares sentences with these, for which no sentence is quoted: tumor (2 papers); Azoospermia (1).